IL6 (interleukin 6)
Diseases named in the same sentence as IL6 in open-access papers (continued):
Sharing a sentence is not in itself a finding about the gene and the disease.
COVID-19 (continued). "This blueprint also stated the variability of IL-6 concentrations in patients with COVID-19." (PMID 34012390, 2021). "Also, an Italian study suggested a score composed of IL-6 and other six variables as a useful predictor of a composite endpoint of severe COVID-19 and/or in-hospital death." (PMID 33679753, 2021). "It was recently reported that IL-1 inhibition, but not IL-6 inhibition, was associated with a 55% reduction in mortality risk in patients with severe COVID-19 who presented with respiratory insufficiency and hyper inflammation." (PMID 34715834, 2021). "IL-8, encoded by the CXCL8 gene, was proposed to be a better biomarker of the COVID-19 outcome than IL-6, as IL-6 may activate the pro- and anti-inflammatory pathways." (PMID 34571838, 2021). "Moreover, recent data indicate that patients with high CRP levels, together with elevated IL-6 and PCT, are more likely to experience severe complications due to the cytokine storm associated with coronavirus disease (COVID-19)." (PMID 33790693, 2021). "Indeed, thromboembolism was determined in systematic post-mortem examinations of COVID-19 patients; therefore, treatment of the pathogenesis of COVID-19 with low-molecular-weight heparin is recommended, which also reduces IL-6." (PMID 34869231, 2021). "Hyperferritinaemia in COVID-19 patients is attributed primarily to inflammatory cells at the site of infection, such as macrophages, and increased pro-inflammatory cytokine secretion, such as IL-6." (PMID 34436155, 2021). "A study conducted in 43 adult COVID-19 patients showed high levels of IL6 could be positively related to disease severity." (PMID 34513735, 2021). "Several studies have correlated increased IL-6 levels with COVID-19 severity and mortality." (PMID 34539644, 2021). "Also, ROC curve cut-off values were reported to indicate a moderate increase of IL-6 for defining COVID-19 headache." (PMID 34384355, 2021). "Moreover, accumulating evidence suggests that a subgroup of patients with severe COVID-19 have a cytokine storm syndrome, characterized by increased interleukin (IL)-1, IL-6, IL-7, interferon-γ inducible protein 10 among others." (PMID 33917093, 2021). "Interleukin 6 is an attractive target with important implications in COVID-19 pathophysiology." (PMID 33660966, 2021). "GM-CSF+ IL-6+ CCR6+ Th17 cells have been detected in the blood of COVID-19 patients." (PMID 35126355, 2021). "However, the study performed on our patients indicates significantly higher concentrations of ferritin and IL-6 in patients with COVID-19 requiring intensive care comparing with those hospitalized in non-ICU departments." (PMID 34372587, 2021). "In severe cases of COVID-19, the plasma level of IL-6 is especially high." (PMID 33761870, 2021). "In conclusion, plasma HMGB1 and IL6 at ICU admission may serve as prognostic biomarkers in critically ill COVID-19 patients." (PMID 33939645, 2021). "The use of tocilizumab can suppress IL-6 levels and can reduce the symptoms of COVID-19." (PMID 34306612, 2021). "In this study, we longitudinally investigated the dynamics of peripheral immune cells and inflammatory cytokines in 67 COVID-19 patients with different disease severities and found that critical cases showed significantly decreased lymphocyte subsets and increased IL-6 and IL-10 levels on admission." (PMID 33461503, 2021). "Although the precise pathogenesis of the coronavirus disease 2019 (COVID-19) pneumonia remains unsolved, evidence showed that within a complex cytokine storm scenario, SARS-CoV-2 provokes a dramatic increase in IL-6 levels." (PMID 34768455, 2021). "However, reported plasma IL-6 levels in COVID-19 patients appear to be significantly lower on average (10- to 40-fold) when compared with those reported in other non-COVID-19 ARDS cohorts that display signs of a cytokine storm." (PMID 34970706, 2021). "IL-6 is a type of pro-inflammatory cytokine that releases in the severe COVID-19 patients." (PMID 34099831, 2021).
COVID-19 (continued). "IL-6 is elevated in COVID-19 and dengue and is related to the severity of both." (PMID 34394108, 2021). "The direct implication of the cytokines involved in disease pathophysiology and the associated pneumonia, found both in MAS and in COVID-19, is highlighted in preliminary trials against SARS-CoV2, where blockade of IL-6 with tocilizumab showed promising clinical efficacy." (PMID 33717168, 2021). "Because IL-6 is linked to pulmonary fibrosis, for example, during idiopathic pulmonary fibrosis, high IL-6 levels during COVID-19 could promote pulmonary fibrosis; this hypothesis would need further investigation." (PMID 34630379, 2021). "For COVID-19 patients who exhibit cytokine storms or secondary hemophagocytic lymphohistiocytosis (sHLH) accompanied by significantly increased levels of IL-6, ferritin, and D-dimer, these may be potential therapy." (PMID 34305916, 2021). "Therefore, tocilizumab, IL-6 monoclonal antibody has been approved for treatment of severe COVID-19 episodes." (PMID 34684094, 2021). "COVID-19 and AD share common links with respect to angiotensin-converting enzyme 2 (ACE2) receptors and pro-inflammatory markers such as interleukin-1 (IL-1), IL-6, cytoskeleton-associated protein 4 (CKAP4), galectin-9 (GAL-9 or Gal-9), and APOE4 allele." (PMID 33078369, 2021). "Elevated angiotensin II levels can increase inflammatory cytokine levels, like IL-6, which may explain the link between inflammatory lung disease and COVID-19." (PMID 34452063, 2021). "In COVID-19, the high release of IL-6 by T lymphocytes contributes to the cytokine storm." (PMID 33815368, 2021). "If a comparable decline in IL-6 secretion is also induced in patients, infrared treatment could be of real therapeutic benefit for late-stage COVID-19 patients." (PMID 34552685, 2021). "The significant increase of inflammatory biomarkers, such as serum amyloid A, IL-6, and CRP in severe COVID-19 patients, are directly or indirectly linked to adipocytes with sub-clinical low-grade inflammation that further exacerbates COVID-19 severity in individuals with obesity." (PMID 34220807, 2021). "Another possible mechanism of deferoxamine in decreasing the COVID-19 severity course would be through reducing IL-6 values and diminished endothelial inflammation, which could prevent COVID-19-induced MOF." (PMID 34812049, 2021). "Marked elevations of IL-6 and other inflammatory markers demonstrating cytokine activation may indicate the role of IL-6 inhibitors like sarilumab, siltuximab and tocilizumab in ACovCS and severe COVID-19." (PMID 32943474, 2021). "The pathogenesis of the acute pulmonary injury related to COVID-19 is similar to that occurring in other disorders that induce hyperinflammatory state with a release of high amounts of pro-inflammatory cytokines, mainly, IL-1, IL-6 and TNF-α." (PMID 33925423, 2021). "A study in 71 patients hospitalized with COVID-19 found that levels of IL-6 and IL-10 were significantly higher in critically ill patients with severe COVID-19 compared to those with severe or mild form of disease, and patients with higher levels of IL-10 had shorter overall survival." (PMID 34945111, 2021). "There are also suggestions for using IL-6 as a biomarker for COVID-19 severity." (PMID 33723251, 2021). "Anti-IL-6 (tocilizumab) treatment also had positive or equivocal results on COVID-19 outcomes." (PMID 34943795, 2021). "The impact of IL-6 induction in the context of COVID-19 cytokine storm remains to be addressed in subsequent studies and in vivo experiments, but the clear net anti-inflammatory profile of EPs 7630 found in our experiments indicates that strong inflammatory signaling through IL-6 appears unlikely." (PMID 34759825, 2021). "Elevated serum cytokines, including interleukin-6 (IL-6), IL-10, tumor necrosis factor-α (TNF-α) and interferon-γ, may cause fatal ARDS and coagulation disorders in COVID-19 patients." (PMID 34001244, 2021).
COVID-19 (continued). "Thirdly, we found that the evolutionary increase in ACE2, and especially the IL-6 gene response to inflammatory and IFN signaling may serve as an epigenetic marker for COVID-19 susceptibility in some animal species, including humans." (PMID 33503821, 2021). "Therefore, noninvasive (auricular) vagal nerve stimulation is discussed as a therapeutic strategy for AD as well as severe COVID-19, since a downregulation of inflammatory pathways (reduction of IL-6 levels) is expected as a result." (PMID 34942956, 2021). "Both IL-6 and IL-10 are reported to be predictors of COVID-19 severity." (PMID 34384355, 2021). "It indicated that IL-6 and D-dimer were exactly related to the occurrence of severe COVID-19 in adult patients, and their combined detection had the highest specificity and vulnerability for early prediction of the severity of patients with COVID-19." (PMID 33670394, 2021). "COVID-19 patients have elevated levels of IL-6, which is a likely driver of NETosis." (PMID 34737734, 2021). "Compared with severe SARS and MERS, characteristic clinical and pathological features of severe COVID-19 include milder thrombocytopenia, higher IL-6 levels, and more frequencies of extrapulmonary manifestations and diffuse microvascular thrombosis with NETosis." (PMID 34769508, 2021). "Therefore, it has been suggested to use an IL-6 inhibitor for the treatment of severe COVID-19 cases." (PMID 34108851, 2021). "Pro-inflammatory cytokine IL-6 exhibited an increased concentration in blood in COVID-19 patients and could participate in general inflammatory state observed in the disease." (PMID 34386007, 2021). "Plasma IL-6 was measured in 133 hospitalized COVID-19 patients." (PMID 35111793, 2021). "IL-6 represents one of the most studied cytokines in COVID-19." (PMID 33673697, 2021). "Moreover, longitudinal analysis identified IL-6 and MCP-1 as the main risk factors related to mortality in hospitalized COVID-19 patients." (PMID 34539631, 2021). "Indeed, the clinical manifestation of COVID-19 is marked by higher concentrations of IL-2, IL-6, IL-8, TNFα, IFNγ, MCP1, MIP1α, IP-10, and GMCSF in patients’ blood." (PMID 34866574, 2021). "COVID-19 patients are reported to have frequently shown abnormal laboratory test results indicative of a cytokine storm, including elevated levels of serum ferritin and IL-6, which makes it possible to diagnose HLH as well." (PMID 34439868, 2021). "Immune effector cells can release large amounts of pro-inflammatory cytokines (TNF-α and TGF-β, IFN-α, IFN-γ, IL-1β, IL-6, IL-12, IL-18 or IL-33) and chemokines (CCL2, CCL3, CCL5, CXCL8, CXCL9 or CXCL10) in response to SARS-CoV-2 infection." (PMID 34360616, 2021). "In addition, clusters #3 and #4 significantly correlated with the level of oxygen supplementation, the proinflammatory cytokine IL-6 indicated in COVID-19 pathophysiology, and the length of stay in the hospital." (PMID 34228753, 2021). "For example, coagulation factor deficiencies with tocilizumab, and peripheral embolism and thrombosis with sarilumab, are presumably related to the use of these anti-IL6 to treat the pro-coagulative cytokine storm, characteristic of severe COVID-19, suggesting an indication bias." (PMID 34955821, 2021). "Several published works show an increase of IL-10 in critically ill COVID-19 patients despite its general anti-inflammatory nature, even proposing this protein as a prognostic biomarker, together with other well-known inflammatory cytokines such as IL-6." (PMID 35087533, 2021). "The key role of IL-6 in COVID-19 was also emphasized, and it could be used as a therapy target in the treatment of patients with COVID-19." (PMID 33746945, 2021). "Moreover, a significant correlation between COVID-19 severity and the serum concentrations of IL-1, IL-2, IL-6, IL-7, IL-10, TNF-α, G-CSF, CCL2, CCL3, CXCL8, and CXCL10 has been observed." (PMID 34209845, 2021).
COVID-19 (continued). "Moreover, there is a significant increase in the IL-6 levels in severe cases of COVID-19, when compared to mild COVID-19 cases." (PMID 33969006, 2021). "Several studies have already been published about the effect of anti-IL6 agents in COVID-19." (PMID 33679753, 2021). "The cytokine storm in COVID-19 is characterized by a high expression of IL-6 and TNF-α." (PMID 34205975, 2021). "IL-6 has also been shown to be involved in the pathophysiology of COVID-19." (PMID 33435405, 2021). "Severe COVID-19 patients had significantly higher IL-6 levels than non-severe patients, suggesting a pathogenic role of IL-6 in a cytokine storm." (PMID 34367188, 2021). "To functionally test the role of cytokines on the viability of lymphocytes, we treated PBMCs isolated from healthy donors with selected groups of cytokines (e.g., IL-10, IL-15, IL-18, IL-8, IL-6, IL-1RA, IL-2RA, IL-4) for 36 h, using the maximum doses detected in COVID-19 serum." (PMID 34103487, 2021). "This miRNA was shown to reduce the expression of IL-6 in TNF-α stimulated MH7a cells and so its reduction may be partially responsible for the characteristic IL-6 increase seen in COVID-19 patients." (PMID 34320031, 2021). "Suppression of pro-inflammatory IL-1 family members and IL-6 has been shown to have a therapeutic effect in many inflammatory diseases, including viral infections, and has been explored as a potential therapeutic avenue in COVID-19." (PMID 33465050, 2021). "Similarly to some previous studies, we observed increased peripheral blood levels of immune-inflammatory parameters such as AST, LDH, CRP, IL6, and PT in COVID-19 patients compared to controls." (PMID 34945761, 2021). "Therefore, Mylc lines can be used to analyze two dangerous adverse effects, the enhancement of virus infection and the augmentation of IL-6 production, present in the sera of COVID-19 patients." (PMID 34887501, 2021). "Variants in cytokine genes such as IL1B, IL1R1, IL1RN, IL6, IL17A, FCGR2A, and TNF could be related to disease susceptibility and cytokine storm, and/or COVID-19 complications (e.g., venous thrombosis)." (PMID 33868239, 2021). "Additionally, another inflammatory marker for COVID-19 is elevated IL-6 in severe cases as seen in the present study." (PMID 33633875, 2021). "IHC showed that high levels of IL-6 and IL-1β could be observed in the spleens and the LNs from COVID-19 autopsies, whereas, sections from trauma victims were absent of IL-6 and IL-1β expression." (PMID 33995382, 2021). "In some patients with COVID-19, IL-6 levels rise more than 1,000 fold above normal range." (PMID 35155571, 2021). "In addition, the systemic increase of pro-inflammatory cytokines such as interleukin-6 is also believed to be a major contributor of inducing hypercoagulable state in COVID-19." (PMID 33205744, 2021). "Additionally, a recent retrospective study collected data from 121 patients with COVID-19 and found increased levels of IL-6 (35.2%) and IL-10 (64.4%) on hospital admission." (PMID 34251989, 2021). "We found that severe COVID-19 patients displayed, as extensively already reported, high level of circulating inflammatory cytokines, including IL-6, TNF-α, IL-1β and chemokines such as CXCL-10, CCL-2 and CXCL-8 contributing to the diffuse inflammatory status and the so-called cytokine storm." (PMID 34473805, 2021). "In our cohort, the serum levels of IL-6 and SP-D were elevated dramatically in severe patients, suggesting that SP-D, together with IL-6, may participate in the complex immune dysregulation process and contribute to the pathogenesis of severe COVID-19." (PMID 34344306, 2021). "It has been suggested that statins may lower IL-6 levels, and thus improve the prognosis of COVID-19 patients, by inhibiting Toll-like receptor 4 (TLR-4)." (PMID 33920709, 2021). "Since the critical role of IL-6 in severe pulmonary injury in COVID-19, humanized monoclonal antibodies targeting the IL-6 receptor subunit alpha may have a therapeutic role." (PMID 33765288, 2021).
COVID-19 (continued). "It should also be noted that IL-6 triggers the most severe inflammatory storm in COVID-19 patients." (PMID 34054974, 2021). "Levels of IL-6, mediator of the acute inflammatory response, and C-reactive protein (CRP), non-specific marker of inflammation, in these patients continue to increase over time and is significantly associated with ARDS and death in COVID-19 patients." (PMID 34595175, 2021). "Furthermore, the involvement of C5a in the inflammatory process of COVID-19 is supported by identifing in patients with COVID-19, increased monocyte production of inflammatory cytokines, such as IL-6, TNF-α, and CCL2." (PMID 33669011, 2021). "IL-6 and D-dimer have recently been shown to be closely related to severe cases of COVID-19." (PMID 34578370, 2021). "Of note, in DM patients with COVID-19, IL-6 links to associated metabolic disorders and cardiovascular complications, so IL-6 antagonist tocilizumab may attenuate the clinical course and outcomes in DM patients with COVID-19-induced pneumonia." (PMID 34124187, 2021). "In addition, inflammation-related molecules, which have been proven to be related to AKI in previous studies, including MCP-1 and IL-6, are also upregulated and enriched in the kidney distal tubules of COVID-19 patients." (PMID 34136484, 2021). "Association between serum IL-6 levels (as exposure) and severity of COVID-19 (as the outcome) in infected patients with and without MAFLD at hospital admission." (PMID 33763027, 2021). "Indeed, IL-6 is crucial in regulating the inflammatory response, and increased IL-6 levels in COVID-19 patients have been repeatedly related to the severity and prognosis of this disease." (PMID 34126960, 2021). "Hence, during the hospitalizations of COVID-19 patients, monitoring plasma or serum gp96 and IL-6 levels has a certain value and better effectiveness in early warnings of disease severity." (PMID 34817280, 2021). "Inflammatory cytokine signatures, such as IL-6 and IL-8, could be used to predict COVID-19 severity and survival." (PMID 34925252, 2021). "For example, IL-6, CRP, and hypertension were ideal predictors for the progression of COVID-19, while older age, high Sequential Organ Failure Assessment (SOFA) score and D-dimer greater than 1 μg/L were risk factors for in-hospital death in COVID-19 patients." (PMID 33987176, 2021). "We consider IL-6 measurement to be a useful biomarker in clinical care of COVID-19 patients." (PMID 33305624, 2021). "When we analyzed the immune cells and cytokines between COVID-19 and cancer patients, we discovered that there were similar changes in these biomarkers, such as low lymphocytes, high monocytes, high neutrophils, high IL-6, and high IL-10." (PMID 34712741, 2021). "As the increased level of IL-6 also correlates with COVID-19 severity and mortality, researchers hypothesise that blocking cytokine signaling may assist in the clearance of the SARS-CoV-2 virus." (PMID 34205217, 2021). "IL-6 is a signature cytokine of inflammation correlating with COVID-19 mortality." (PMID 34326843, 2021). "In addition, most recent progress on inhibitors of IL-6 or its receptors, tocilizumab, sarilumab, siltuximab and olokizumab, is also summarized from perspective of clinical trials for COVID-19 therapy." (PMID 37287491, 2021). "Moreover, IL-6 is a proinflammatory cytokine with significantly elevated levels in severe COVID-19 patients and has also been found to play a role in protection against Aspergillus." (PMID 34940403, 2021). "HMGB1 and IL-6 levels were elevated in COVID-19 patients (n = 60) compared with healthy subjects." (PMID 33939645, 2021). "Like cancers, IL6 inhibition of corticosteroids such as dexamethasone and prednisone or methylprednisolone may also be evaluated to manage severe COVID-19 patients suffering from CVDs." (PMID 34067609, 2021). "Thus, temporal and precise mechanistic therapy targeting IL-6 and NETosis shall potentially benefit critically ill patients of both COVID-19 and sepsis." (PMID 34775962, 2021).